HR (HR lysine demethylase and nuclear receptor corepressor)
Diseases named in the same sentence as HR in open-access papers (continued):
Sharing a sentence is not in itself a finding about the gene and the disease.
triple-negative breast carcinoma (30 papers, 2015 to 2026). An invasive breast carcinoma which is negative for expression of estrogen receptor (ER), progesterone receptor (PR), and human epidermal growth factor receptor 2 (HER2). "Nevertheless, it is known that the overall survival of women diagnosed with HR+/HER2+ is better when compared to triple negative breast cancers, since HR+/HER2+ tumors may respond to targeted therapies." (PMID 29514651, 2018). "The majority (69%) of patients had HR+/HER2- disease, followed by HER2+ disease (19%), and triple-negative breast cancer (TNBC, 12%)." (PMID 40647452, 2025). "We identified 111 patients with MBC and LMD, including patients with the following subtypes: HR+/HER2− (n = 53, 47.7%), HER2+ (n = 30, 27.0%), and triple negative breast cancer (TNBC; n = 28, 25.2%)." (PMID 38888796, 2024). "The HR-/HER2- group, as the triple-negative breast cancer type, was considered resistant to CDK4/6i with higher ‘‘p-YB-1/PARP1’’ expression." (PMID 38037159, 2023). "The median duration of systemic therapy was 11, 8.4, 7.3, and 0.8 years in the hormone receptor-positive (HR+)/human epidermal growth factor receptor 2-negative (HER2−), HR+/HER2+, HR−/HER2+, and triple-negative breast cancer (TNBC) patients, respectively." (PMID 37835414, 2023). "Single HR+ tumors without HER2 overexpression (ER + PR-HER2- or ER-PR + HER2-) were associated with poorer survival than ER + PR + HER2- tumors, and had comparable poor survival to ER-PR-HER2- tumors (triple-negative breast cancer)." (PMID 25880075, 2015). "Both triple-negative breast cancer (TNBC: 36%) and hormone receptor-positive, HER2 negative (HR+/HER2−) MBC (64%) were seen." (PMID 36333333, 2022). "Last, it was found that some triple-negative breast cancer (TNBC) cell lines showed sensitivity to palbociclib with obvious growth inhibition, and the efficacy of palbociclib on TNBC was irrespective of the status of HR and HER2." (PMID 38037159, 2023).
breast tumors (10 papers, 2019 to 2025). "First, we employed the microenvironment cell populations-counter (MCP-counter) analysis to depict the microenvironment features of HR+/HER2– breast tumors." (PMID 39531335, 2024). "To follow up on these observations, in the current research we investigated further the impact of TME Stimulation on pro-metastatic characteristics and functions of HR+/HER2− breast tumor cells, focusing mainly on the mechanisms accounting for CSC enrichment." (PMID 37190183, 2023). "TCGA data was extracted from data from primary breast tumors of patients categorized as luminal A according to their PAM50 subtype classification (mostly equivalent to the HR+/HER2− subtype)." (PMID 37190183, 2023). "The TME Stimulation model that we have used in this study has combined the hormonal, inflammatory and growth-promoting arms of the TME; however other arrays of TME setups can be active in HR+/HER2− breast tumors, as well as in other malignancies." (PMID 37190183, 2023). "Continued monitoring of the MCC/WRNMMC cohort is critical to determine whether disparate survival rates diverge significantly after 10 years, especially for women with HR+/HER2− breast tumors." (PMID 36942312, 2023). "Though all 8 patients had HR+/HER2-negative disease, the breast tumors exhibited disparate disease characteristics, including in tumor grade, Ki67, and histology." (PMID 38502947, 2024). "We uncovered 20 novel fusion transcripts from 75 breast tumors of 3 subtypes: TNBC, HER2+, and HR+." (PMID 37744342, 2023). "Classically, breast tumors are characterized by the presence or absence of a hormone receptor [HR; estrogen receptor (ER) or progesterone receptor (PR)) and/or the overexpression of human epidermal growth factor receptor-2 (HER2)]." (PMID 30813596, 2019).
metastatic disease (8 papers, 2020 to 2025). "From a database of 202 women with HR+/HER2− ABC who received treatment with fulvestrant from 2005 to 2017 at the 3 participating Institutions were retrieved 74 patients who underwent a diagnostic biopsy for advanced or metastatic disease before treatment." (PMID 35896637, 2022). "HR and HER2 status of metastatic tumors were confirmed for twenty-one patients from the CN cohort, with 18 patients maintaining HR+ and HER2− status, while 3 patients became HR- and HER2−." (PMID 34471951, 2021). "In the US cohort, the HR and HER2 status of metastatic tumor was confirmed for 23 patients, with all patients maintaining HR+ and HER2− status." (PMID 34471951, 2021). "Forty-three patients with HR+, HER2-negative mBC underwent both a metastatic tumor biopsy and a liquid biopsy at the time of disease progression." (PMID 33777770, 2021). "Tissue was collected from 89 patients with HR+/HER2− MBC, including those with recurrent and/or metastatic disease, receiving palbociclib plus an aromatase inhibitor or fulvestrant at Samsung Medical Center and Seoul National University Hospital from 2017 to 2020." (PMID 37475004, 2023).
Hyperglycemia (3 papers, 2024). An increased concentration of glucose in the blood. "Earlier identification and intervention for treatment-induced hyperglycemia can potentially improve clinical management and lead to better outcomes for patients with HR+/HER2− ABC." (PMID 38439079, 2024).
hypotrichosis (3 papers, 2012 to 2024). A congenital condition, usually due to genetic aberrations, that is characterized by a lack of hair growth on the head and/or body. "Mutations disrupting the uORF in the 5′UTR of the gene encoding the human hairless homolog (HR) and resulting in increased translation of the gene, have been associated with Marie Unna hereditary hypotrichosis, an autosomal dominant form of genetic hair loss." (PMID 22538991, 2012).
breast disease (2 papers, 2017 to 2023). "In the EAP, a total of 242 patients with HR+/HER2- advanced breast disease from 42 centers in the US were assigned to single-arm palbociclib 125 mg/d (3 weeks on, 1 week off) in combination with letrozole 2.5 mg/d (continuous daily dosing) until disease progression." (PMID 28978004, 2017). "Pre-therapy clinical N stage > 0, positive pre-therapy lymph node biopsy, estrogen and progesterone receptor positivity, Ki67 < 50%, HR + /HER2− tumors, and residual breast disease had higher likelihood of residual lymph node disease after NAC (p < 0.001)." (PMID 37286892, 2023).
ductal carcinoma in situ (2 papers, 2022). "Most of the women had early cancer stage (ductal carcinoma in situ/stage I; 53.5%), and the most frequent subtype was HR+/HER2- (76.4%), followed by HER2+ (15.4%) and triple-negative (8.2%)." (PMID 35455838, 2022). "A total of 53.5% of all of the women were diagnosed with stage 0 (ductal in situ carcinoma) or I, and the most frequent type of cancer was HR+/HER2− (76.4%), followed by HER2+ (15.4%) and triple negative (8.2%)." (PMID 35323373, 2022).
hypotrichosis 4 (2 papers, 2022 to 2023). "The 5′-UTR mutation of the human HR gene causes a rare autosomal dominant alopecia disease: Marie Unna hereditary hypotrichosis (MUHH), which is characterized by an abnormal hair density on the scalp, eyebrows, eyelashes, or body." (PMID 34980884, 2022).
invasive breast carcinoma (2 papers, 2020 to 2024). A carcinoma that infiltrates the breast parenchyma. "The result of her biopsy reported that the tumor histology was invasive breast cancer with good differentiation and that the breast subtype was HR–/HER2+." (PMID 33042815, 2020).
lobular breast carcinoma (2 papers, 2024). "Further diagnostic assessments unveiled an HR+/HER2- bilateral lobular breast carcinoma with synchronous bilateral orbital metastases." (PMID 38322413, 2024).
ovarian carcinoma (2 papers, 2019 to 2021). A malignant neoplasm originating from the surface ovarian epithelium. "The search for markers of ovarian cancer development was carried on in the further part of the study by an analysis of the polymorphisms of HR genes (RAD51 and BRCA1)." (PMID 30712190, 2019).
anemia (1 paper, 2024). A reduction in the number of red blood cells, the amount of hemoglobin, and/or the volume of packed red blood cells. "For second-line treatment, the TNBC subgroup (n = 64) documented anemia (32.8%) and the HR+/HER2-negative subgroup (n = 68) documented neutropenia (17.7%) as the most commonly experienced toxicities." (PMID 38817906, 2024).
diabetes mellitus (1 paper, 2022). A metabolic disorder characterized by abnormally high blood sugar levels due to diminished production of insulin or insulin resistance/desensitization. "Moreover, a single arm open label pilot trial is ongoing to assess the combination of dapagliflozin, a sodium/glucose cotransporter-2 (SGLT-2)-inhibitor used to treat diabetes mellitus, with alpelisib + fulvestrant in patients with HR+/HER2− metastatic BC." (PMID 35565291, 2022).
lymph node disease (1 paper, 2023). "Clinical N stage > 0, positive pre-therapy LN biopsy, ER positivity, PR positivity, Ki67 proliferative index < 50%, and patients with HR + /HER2 tumors predicted higher risk of residual lymph node disease." (PMID 37286892, 2023).
lymphopenia (1 paper, 2022). Reduction in the number of lymphocytes. "Among the 154 patients with lymphopenia, 16.9% (26/154) patients were triple‐negative, 64.3% (99/154) were HR+/HER2‐ and 18.8% (29/154) were HER2+ subtype." (PMID 34390318, 2022).
melanoma (1 paper, 2020). A malignant, usually aggressive tumor composed of atypical, neoplastic melanocytes. "One HR−/HER2+ patient died of a melanoma and one patient of this subgroup, treated with Herceptin and Perjeta, relapsed after 32 months." (PMID 32558176, 2020).
multiple myeloma (1 paper, 2023). "Herein, we reported outcomes for an HR+/HER2- MBC patient diagnosed with multiple myeloma and treated with abemaciclib and exemestane, who had cancer progression after treatment with palbociclib and fulvestrant." (PMID 36698413, 2023).
rectal cancer (1 paper, 2019). A primary or metastatic malignant neoplasm that affects the rectum. "Next generation sequencing data from 145 rectal cancer retrieved from TCGA were used to evaluate the mutational status of 23 MMR genes (KEGG: hsa03430) and 41 HR genes (KEGG: hsa03440) in association to GII." (PMID 31192117, 2019).
tumor (68 papers, 2008 to 2026). "Although development of immune checkpoint inhibition strategies (ICI) targeting tumor-infiltrating lymphocytes (TILs) within the tumor microenvironment has revolutionized cancer treatment, patients with HR+/HER2- BC have derived limited benefit." (PMID 40989687, 2025). "The most prevalent tumor subtype among patients with invasive eBC was HR+ HER2− (2038, 63.1%), followed by HER2+ (10.5%) and TNBC (9.0%)." (PMID 39796772, 2025). "This panel of genes includes trefoil factor family proteins, TFF1 and TFF3, which have been shown to be upregulated in BL immunohistochemistry tumor samples from patients with HR+/HER2- mBC who experience late progression on CDK4/6i therapy." (PMID 39955556, 2025). "CD68 expression was significantly higher in the tumor stroma of metastases compared to the corresponding primary tumors (p = 0.011), with this difference primarily driven by HR+/HER2- tumors (p = 0.016)." (PMID 40510346, 2025). "Although a majority of ILC tumors were HR+/HER2− and low to intermediate grade, we found that low SES was associated with more aggressive tumor features, including higher grade and increased LVI." (PMID 40569506, 2025). "The primary tumor site is the upper-outer quadrant of the breast, with right-side laterality, and a subtype of HR+/HER2-." (PMID 41356963, 2025). "We next assessed protein expression levels of KIFC2, USP9X, and CDK4 in 45 tumor samples from patients with HR+/HER2– BC by IHC." (PMID 40299549, 2025). "Our results documented this type of change, in which three luminal B-like HER2+ tumours lost HR expression and four luminal B-like HER2+ lost HER2 amplification." (PMID 37370679, 2023). "Patients with an HR+/HER2−, PIK3CA wt tumor appeared to have shorter mOS, 18.9 months (CI 14.1–25.1), compared to patients with a tumor harboring any PIK3CA mutation (23.4 months; CI 17.0–27.6)." (PMID 37178424, 2023). "In 30%–40% of HR+/HER2– BC patients, activating mutations were found in the PIK3CA gene, making it one of the most commonly altered genes in this type of tumor." (PMID 38148576, 2023). "Regarding the primary tumor, the most frequent pathological type was ductal (93%), the most frequent pathological grade was 3 (50%), and the molecular subtypes were mainly HR+/HER2− (56%), then triple-negative (TN) (32%), and HER2+ (12%)." (PMID 35205679, 2022). "Of the remaining 1474 patients, the mean age was 58.8 ± 12.9 years and the most common tumor biology was HR+/Her2− (76.1%), followed by Her2+ (14.7%) and triple negative (9.2%)." (PMID 35330381, 2022). "Although a difference in grading was obtained in the different subgroups, most TNBC patients (42/51; 82%) and HR−/HER2 + patients (8/10; 80%) had grade III tumours whereas most of the HR+/HER2− patients had a grade II tumour (10/14; 71%), respectively." (PMID 32558176, 2020). "The molecular subtype was discordant for the two pairs (14%)—the primary tumor was HR+/HER2–, whereas the metastasis was TN." (PMID 31086113, 2019). "Several genes, such as TMPRSS4, STAR, ST7L, HAS3, FGFR3, CASZ1 and HR, were found to have gene expression changes at the very earliest stages of tumor thickening." (PMID 18442402, 2008). "Tumor biological subtype overall was 40% HR+/HER2−, 37% HER2+, and 23% TNBC." (PMID 39120840, 2024). "Focusing on TME-derived factors, our previous findings have demonstrated the impact of a combined stimulus representing three key arms of the tumor milieu of HR+/HER2− tumors—including hormonal, inflammatory and growth stimulating factors—on the pro-malignancy phenotype of the cancer cells." (PMID 37190183, 2023). "In addition to the tumor size and the lymph node metastasis, many biological factors, including the tumor grade, growth activity (Ki67 index), expression of HR and HER2 status and multigene assays, are taken into consideration when deciding on adjuvant treatment strategies." (PMID 32472474, 2020).
tumor (continued). "In all, 18 patients (51%) of the full study group were in the 1st line of therapy at time of test initiation and 12 (48%) belonged to the HR+/HER2- cohort; 6 (17%) patients had an HER2-amplified and 5 (14%) patients a triple negative tumor." (PMID 39839709, 2025). "Tumours meeting the criteria of the FAST-Forward trial more often received five fractions if they were grade 1 or 2, HR+/HER2-, <30 mm or pN0." (PMID 38979479, 2024). "The tumor size was smaller for HR+/HER2−, HER2+ was more likely to present as NME, homogeneous enhancement was mostly seen in HR+, and the peritumoral edema was mostly present in HER2+ and TN." (PMID 38067374, 2023). "Conversely, camizestrant has demonstrated clinical activity in patients with HR+/HER2− metastatic breast cancer with a variety of ESR1m, including Y537S, and reduces Y537S ESR1m levels in circulating tumor DNA." (PMID 37725704, 2023). "The most common BC subtypes were triple-negative (n = 16), HR+/ERBB2− (n = 15), and ERBB2+ (n = 9), with one missing data of the primary tumor." (PMID 32591580, 2020). "In general, HR+/HER2− patients mostly presented with T1 tumours (9/14; 64%) and TNBC patients (27/51; 53%) as well as HR−/HER2+ patients (5/10; 50%) with T2 tumours, respectively." (PMID 32558176, 2020). "In terms of tumor subtypes determined by HR and HER2, HR+ /HER2− subtypes were observed in 2039 patients (77.8%), HR+ /HER2+ in 154 (5.9%), HR− /HER2+ 176 (6.7%), and HR−/HER2− (triple negative; TN) in 253 (9.6%)." (PMID 32472474, 2020). "Additionally, 113 normal and 497 HR+/HER2- tumor tissue samples from the TCGA-BRCA cohort were analyzed to identify differentially expressed genes between normal and tumor tissues." (PMID 40936892, 2025). "Second, to accommodate clinical practice and minimize potential confounding factors, all enrolled patients received trastuzumab, possibly resulting in the study not covering HR+/HER2+ patients with tumor sizes smaller than 0.5 cm." (PMID 38185807, 2024). "Furthermore, to explore whether HR deficiency can indeed benefit TNBC patients’ response to ACT treatment, we determined the ACT chemotherapy failure-free interval (FFI) of patients based on the period from the end of treatment to tumour progression/recurrence or death." (PMID 34465315, 2021). "Ninety-two tumours were TNBC, 42 were HR−/HER2+ and 46 were HR+/HER2−." (PMID 28761741, 2017). "The significance of tumor size was limited to HER2− subtypes, including HR+/HER2− and TNBC." (PMID 28409241, 2017). "A total of 87 FFPE tumour specimens came from three major IHC subclasses and were composed of 24 ER−/PR−/HER2− (designated TN); 8 ER−/PR−/HER2+ (designated HER2+); 8 ER+/PR-/HER2+ 11 ER+/PR+/HER2+ 13 ER+/PR−/HER2− and 23 ER+/PR+/HER2− (designated HR+)." (PMID 22067903, 2011). "Regarding the relationship with tobacco by tumor types, we have not found differences among them in pre-menopausal cancers, probably due to the low number of cases of HER2+ and TN tumors, as the HR+ subtype constitutes >70% of all tumors in this group." (PMID 38034128, 2023).